THBS2 (thrombospondin 2)
Diseases named in the same sentence as THBS2 in open-access papers (continued):
Sharing a sentence is not in itself a finding about the gene and the disease.
gastric cancer (continued). "While, the expression of THBS2 protein in gastric cancer did not have correlation with TNM stage, the depth of tumor invasion depth, lymph nodes metastases, HER2 expression or the Lauren classification." (PMID 36842141, 2023). "Moreover, the MSLN, SPP1, THBS2, SPARC, FN1, IGFBP7, VCAN were up-regulated in gastric carcinoma samples, while FGA was down-regulated." (PMID 36842141, 2023). "Nevertheless, the specific effect of THBS2, in addition to its clinical value for gastric cancer, is not disclosed now." (PMID 34659407, 2021). "Upregulation of THBS2, OSMR and CHI3L1 was verified in EMT-induced gastric cancer cell line." (PMID 33585016, 2020). "Furthermore, significant upregulation of candidate genes including THBS2, OSMR and CHI3L1 verified the role of these proteins in gastric cancer invasiveness." (PMID 33585016, 2020). "The results showed that 8 up-regulated genes (FN1, COL3A1, FBN1, BGN, COL5A2, THBS2, COL5A1 and SPARC) and 1 down-regulated gene (ATP4A) may be the central genes in gastric cancer." (PMID 32742441, 2020). "In our study, we found MVD was significantly correlated with THBS2 protein expression (P < 0.001) in gastric cancer, but not with clinical features and clinical prognosis." (PMID 25262009, 2014). "Furthermore, the protein expression difference of THBS2 and VCAN were detected in human gastritis and gastric cancer, and the correlation between THBS2 and VCAN and gastric cancer was speculated." (PMID 36842141, 2023). "On the other hand, THBS2 affected prognosis in gastric cancer may not only through regulating the angiogenesis, but in some other manners like regulating ECM remoulding and inhibiting the proliferation of gastric cancer cells." (PMID 25262009, 2014). "Previous reports implied THBS2 could regulate tumour angiogenesis, yet none was reported in gastric cancer." (PMID 25262009, 2014).
colorectal cancer (31 papers, 2016 to 2025). A primary or metastatic malignant neoplasm that affects the colon or rectum. "This study aimed to investigate the biological role of THBS2 in various types of cancers and the mechanisms underlying the malignant progression of colorectal cancer (CRC)." (PMID 37884956, 2023). "Thrombospondin 2 (THBS2), as a secreted protein, was confirmed to be highly expressed in different cancers including colorectal cancer and its high expression was associated with poor prognosis." (PMID 37500893, 2023). "Thrombospondin 2 (THBS2) is a glycoprotein with a role in tumor growth, angiogenesis, and metastases, with high expression found to be associated with poorer survival in colorectal cancer at the mRNA and protein level." (PMID 36222710, 2022). "THBS2 is a potential diagnostic marker for pancreatic, gastric, non-small-cell lung, and colorectal cancers." (PMID 35701829, 2022). "An increased expression of THBS2 seems to sustain cancer progression in GC and is associated with a poor prognosis in colorectal cancer." (PMID 35328635, 2022). "THBS2 expression in colorectal cancer was associated with reduced angiogenesis and distant metastasis." (PMID 31612481, 2020). "Our study presents the first line of evidences that THBS2 expression is up-regulated mRNA and increased THBS2 expression is associated with poor overall survival of colorectal cancer." (PMID 27632935, 2016). "The current study investigated a comprehensive evaluation method application in profound prognostic value gene in colorectal cancer and attempted to evaluate a new prognostic candidate gene THBS2 underlying significant value." (PMID 27632935, 2016). "Interestingly, in colorectal cancer, a strong positive correlation was observed between the expression of THBS2 and genes encoding the EMT markers N-cadherin, vimentin, TWIST1, and SNAIL, while there was a negative correlation with CDH1." (PMID 39857742, 2025). "Circulating and histological expression of THBS2 has been demonstrated to be a novel diagnostic and prognostic biomarker for patients with pancreatic cancer, distal cholangiocarcinoma, lung cancer, and colorectal cancer." (PMID 36405394, 2022). "Circulating levels of THBS2 was confirmed to be a potential diagnostic candidate in pancreatic cancer and lung cancer, while the histological expression of THBS2 has been identified to be an independent prognostic biomarker for distal cholangiocarcinoma, colorectal cancer, and urothelial carcinoma." (PMID 36405394, 2022). "THBS2 in colorectal cancer is a prognostic biomarker, and its high expression was correlated with low overall and disease-free survival." (PMID 39857742, 2025). "It has been found that low expression of miR-4728-3p in ulcerative colitis-associated colorectal cancer can influence CAV1, THBS2, and COL1A2 genes as well as focal adhesion signaling, which is related to tumor pathogenesis." (PMID 35733095, 2022). "miR-203a-3p binds to the 3’-untranslated region of THBS2 mRNA, downregulating THBS2 expression and inhibiting colorectal cancer progression and metastasis." (PMID 35008515, 2021). "Collectively all these results reveal that the COL11A1 gene has a positive association and correlation with THBS2, COL10A1, COL5A2, and COL1A2 to upregulate the gene expression to induce the development of colorectal cancer." (PMID 33597969, 2021). "In colorectal cancer, high THBS2 expression was significantly correlated with lymph node metastasis." (PMID 34804159, 2021). "Here we studied the prognostic and immunological role of THBS2 in colorectal cancer (CRC) using bioinformatic analysis." (PMID 34471634, 2021). "Consistent with our results, THBS2 was regarded as a potential prognostic biomarker for colorectal cancer (CRC)." (PMID 33585016, 2020). "Thrombospondin 2 (THBS2), as a secreted protein, was confirmed to be highly expressed in different cancers, including cervical cancer, colorectal cancer and NSCLC." (PMID 32831647, 2020).
colorectal cancer (continued). "The hypergeometric distribution analysis showed that THBS2 have a higher correlation with colorectal cancer when compared with COMP (p = 0.0029)." (PMID 27632935, 2016). "And a comprehensive evaluation by meta-analysis that explored the possible correlation between THBS2 with clinical prognosis in colorectal cancer will be more accuracy." (PMID 27632935, 2016). "High level of THBS2 was associated with poor disease-free and overall survival in a cohort of serous colorectal cancer patients that integrated data combination GEO/TCGA datasets with meta-analysis, suggesting that THBS2 may be a prognostic biomarker of colorectal cancer." (PMID 27632935, 2016). "Here we proposed that the prognosis-related gene THBS2, responsible for cooperativity disorientation, probably contain untapped prognostic resource of colorectal cancer." (PMID 27632935, 2016). "Collectively all these experimental data clearly reveal that the COL11A1 gene along with its associated THBS2, COL10A1, COL5A2, and COL1A2 might serve as a prognostic biomarker for colorectal cancer." (PMID 33597969, 2021). "miR-203a-3p was determined to target THBS2 to inhibit colorectal cancer progression and metastasis; thus, miR-203a-3p may be considered a potentially novel approach to treating colorectal cancer." (PMID 35008515, 2021). "Furthermore, RBP4 and THBS2 have been reported to serve as biomarkers for the diagnosis of colorectal cancer." (PMID 31612481, 2020). "Higher THBS2 expression in colorectal cancer tissue was found compared with normal tissue." (PMID 31612481, 2020). "What is noteworthy is that, NCBI GEO gene expression database of TECs in colorectal cancer and lymphoma also verified the specific high expression of 7 out of these 12 ECM associated genes in TECs from colorectal cancer and lymphoma, i.e. SPON2, BMP-1, FN1, POSTN, THBS2, VCAN and AEBP1." (PMID 29541388, 2018). "With the gradual depth studies, THBS2 might become as a potential biomarker for predicting clinical outcome for colorectal cancer patients." (PMID 27632935, 2016). "THBS2 could be considered as a novel prognostic marker in colorectal cancer." (PMID 27632935, 2016). "The frequent dysregulation of THBS2 in several cancers implies that it is not a specific marker for PDAC or dCCA, and it has been proposed as a diagnostic marker in colorectal cancer, hepatocellular cancer and lung cancer." (PMID 34319497, 2022). "The PathwayMapper tab in cBioPortal servers shows the alteration frequency of COL11A1, THBS2, COL10A1, COL5A2, and COL1A2 over the various pathways on the colorectal cancer dataset using a white to red color scale where the more frequently altering gene shows greater intensity of the red color." (PMID 33597969, 2021). "The potential role of serum RBP4 and THBS2 as biomarker in colorectal cancer (CRC) diagnosis has never been studied." (PMID 29190912, 2017). "According to these data above, we have a preliminary conclusion that serum RBP4 concentrations could be a valuable prognostic factor in colorectal cancer, while THBS2 could not." (PMID 29190912, 2017).
pancreatic cancer (30 papers, 2010 to 2025). "THBS2 expression in pancreatic cancer is mainly present in the stroma and is linked to tumor progression and poor prognosis." (PMID 41373732, 2025). "THBS2 has been largely described as a serum diagnostic biomarker, particularly in pancreatic cancer, which is characterized by high stromal compartments." (PMID 35547750, 2022). "THBS2 has been identified as a diagnostic biomarker and downstream target for various pancreatic cancers in humans and mice, highlighting its central role in the proposed PDAC specific GRN." (PMID 33114263, 2020). "Given the biological similarities of dCCA and pancreatic cancer, further evaluation of THBS2 as a potential diagnostic biomarker of dCCA should be encouraged." (PMID 32887625, 2020). "Both prognostic genes appear to be expressed in the stroma, with upregulation of TAGLN in gastric stromal carcinoma-associated fibroblasts, and increased expression of THBS2 implicated in tumor progression and poor prognosis in pancreatic cancer, excreted by stromal fibroblasts." (PMID 36222710, 2022). "Additionally, upregulation of THBS2 mRNA expression is associated with the progression of gastric, colon, and pancreatic cancer." (PMID 34804159, 2021). "ALPPL2 was reported to be overexpressed in pancreatic cancer cells and THBS2 is mainly produced by stromal cells." (PMID 40897818, 2025). "THBS2 knockdown has been shown to decrease the proliferation, migration and invasion of pancreatic cancer cells in vitro; however, its role in the nerves and PNI needs further investigation." (PMID 40075699, 2025). "Serum thrombospondin-2 in combination with CA 19-9 has potential as a biomarker for distal cholangiocarcinoma and pancreatic cancer." (PMID 34319497, 2022). "We analyzed the roles of THBS2 in the gastric, colon, and pancreatic cancer, since THBS2 is upregulated in these three cancers." (PMID 34804159, 2021). "THBS2 expression was higher in several cancers, including breast, colorectal, esophageal, gastric, liver, lung, and pancreatic cancers." (PMID 34471634, 2021). "SULF1 and THBS2 have both been recently suggested as core regulators of gene co-expression networks in pancreatic cancer." (PMID 33114263, 2020). "In pancreatic cancer, THBS2 expression in cancer cells in vitro inhibited invasiveness through downregulation of matrix metalloproteinase-9 and urokinase-type plasminogen activator." (PMID 32887625, 2020). "For example, thrombospondin-2 was recently identified as highly specific diagnostic marker, complementing CA19-9 in the detection of pancreatic cancer." (PMID 32055023, 2020). "Therefore, it is plausible that ALPPL2+ exosomes in the serum are mainly originated from pancreatic tumor cells whereas THBS2+ exosomes are produced by stromal cells such as cancer-associated fibroblasts." (PMID 40897818, 2025). "With respect to PDAC, recent observations in a cohort of 493 (263 with PDAC) showed that THBS2 serum levels significantly differed and differentiated PDAC from high-risk individuals (familial pancreatic cancer patients) with a 55.9% test sensitivity (at 100% specificity; 100% PPV and 66.5% NPV)." (PMID 36670203, 2023). "The current review study identifies 22 IHC biomarkers as diagnostic tools for pancreatic cancer that embrace: Pentraxin-3, ENO1, REG4, POSTN, CA125, CA242, Galectin-1, Galectin-9, Maspin, pVHL, MUC1, MUC5AC, THBS2, LTBP2, CPA4, IMP3, CD13, Dkk1, KOC, S100P, Mesothelin, PAM4." (PMID 34988027, 2021). "In pancreatic cancer, THBS2 is correlated with THBS1, THBS3, and THBS5." (PMID 34804159, 2021). "In addition, THBS2 has inhibitory effects on the metastasis of malignant melanoma and pancreatic cancer." (PMID 31296790, 2019). "Specifically, pentraxin-3 can discriminate pancreatic cancer from gallstone disease; maspin and pVHL may discriminate pancreatic cancer from mucinous cystic pancreatic neoplasms; THBS2 may differentiate between pancreatic cancer and intraductal papillary mucinous pancreatic neoplasms." (PMID 34988027, 2021).
pancreatic cancer (continued). "Similarly, CN2+THBS2 are both up-regulated by 2-fold in kidney, lung and pancreatic cancer." (PMID 21060876, 2010). "Thrombospondin-2 (THBS2), a GC-regulated ECM–immune bridge protein, correlates with immunosuppressive TME in gastric/pancreatic cancers through impaired T-cell penetration." (PMID 40564001, 2025). "Oncomine analysis of cancer vs. normal tissue confirmed that COL12A1, FN1, ITGA2, LAMB3, LAMC2, THBS2, and VCAN were significantly overexpressed in pancreatic cancer from different datasets." (PMID 34007003, 2021). "THBS2 and VCAN were expressed in both stromal and pancreatic cancer cells, whereas ITGA2, LAMB3, and LAMC2 were solely expressed by pancreatic cancer cells." (PMID 34007003, 2021). "Moreover, in the Pei pancreas dataset, COL12A1, FN1, ITGA2, LAMB3, LAMC2, THBS2, and VCAN mRNA expression levels were higher in pancreatic cancer tissue than in normal pancreatic tissue samples." (PMID 34007003, 2021). "We also investigated the methylation changes at the intergenic enhancer region of THBS2 in various cancers from the TCGA data (HumanMethylation450 BeadChIP) and found that the enhancer of THBS2 was significantly hypo-methylated in colon and liver cancers but not in kidney and pancreatic cancers." (PMID 27016420, 2016).
cervical cancer (29 papers, 2002 to 2025). A primary or metastatic malignant neoplasm involving the cervix. "THBS2 expression was reduced in cervical cancer cells and tissues and was inversely associated with miR-20a expression." (PMID 35456001, 2022). "Furthermore, abnormal expression of miR-214-3p within cervical cancer is associated with tumor cell migration through its interplay with Thrombospondin 2 (THBS2)." (PMID 40191724, 2025). "Studies have shown that autophagy can be induced by regulating targeted genes (such as Bcl-2, THBS2) and pathways (such as Wnt signaling pathway) to promote apoptosis in cervical cancer cell." (PMID 37740231, 2023). "Depletion of miR-20a suppresses proliferation and autophagy and promoted apoptosis by increasing the expression of one of its targets, THBS2 (thrombospondin 2), in cervical cancer cells." (PMID 36230953, 2022). "Knockdown of THBS2 eliminated the antiproliferative, proapoptotic, and anti-autophagic effects of inhibiting miR-20a in cervical cancer cells." (PMID 35456001, 2022). "For example, miR-342-3p can stimulate the malignant potential of NSCLC by regulating the expression of LASP1, and miR-221-3p can promote angiogenesis in cervical cancer by regulating the expression of THBS2." (PMID 35812727, 2022). "Sun and et.al had found that miR-93-5p was up-regulated in cervical cancer cells and promotes cancer progression by down-regulating THBS2/MMPS signal pathway." (PMID 34861847, 2021). "miR-93 has been proved to promote cervical cancer progression by targeting THBS2/MMPS signal pathway." (PMID 34603485, 2021). "A previous report suggested that THBS2 was involved in the proliferation, apoptosis and anti-autophagy regulation of cervical cancer cells by miR-20a." (PMID 32831647, 2020). "A previous document suggested that THBS2 acted as a target of miR-221-3p and participated in lymph node metastasis in cervical cancer." (PMID 32831647, 2020). "As TWIST2 has been shown to be negatively correlated with THBS2 in cervical cancer, we transfected LINC01235 overexpression plasmids into HGC-27 and SGC-7901 cells." (PMID 33206629, 2020). "THBS2 has also been reported to act as important downstream targeting gene of miRNAs to form a miRNAs/THBS2 network for various diseases, such as cervical cancer, human myxoid liposarcoma and renal cancer." (PMID 31432993, 2019). "There may be role variations in different tumor types as THBS2 has been reported to be an inhibitor of angiogenesis in cervical cancer." (PMID 36222710, 2022). "We also analyzed the correlation of ITGA5 with anti‐angiogenesis genes THBS2, PTEN, SERPZNF1, and IL‐10 in cervical cancer based on TCGA dataset, but the correlations were rather modest as the R values ranged between −0.011 and 0.16, though the p values were less than 0.05." (PMID 36999964, 2023).